BCL2 (BCL2 apoptosis regulator)
Diseases named in the same sentence as BCL2 in open-access papers (continued):
Sharing a sentence is not in itself a finding about the gene and the disease.
breast carcinoma (continued). "C. versicolor extract demonstrably reduces BCL-2 expression in breast cancer cells." (PMID 36676192, 2023). "A study indicated that lncRNA APOC1P1-3 could promote breast cancer metastasis by specifically binding miRNA-188-3p to block Bcl-2 inhibition through anoikis-resistance." (PMID 38049825, 2023). "We found that Bcl-2 expression was associated with a higher overall and breast cancer-specific survival, whereas SGK1 and GCR expression did not appear to be associated with survival." (PMID 37370761, 2023). "Additionally, it has been reported that targeted siRNA-mediated silencing of Bcl-2, a common regulator of apoptosis and autophagy, can induce autophagic cell death in breast cancer cells overexpressing Bcl-2." (PMID 37894866, 2023). "Hence, FASN inhibitors enabled breast cancer cells to be sensitive to venetoclax or navitoclax to overcome the insensitivity of monotherapy with BCL-2 inhibitors in vivo." (PMID 37894324, 2023). "However, inhibiting TLK2 leads to the downregulation of ERα, BCL2, and SKP2, causing cell cycle arrest in the G1/S phase and ultimately triggering apoptosis, which can help improve the prognosis of patients with breast cancer." (PMID 38343446, 2023). "The development of BCL2 inhibitors, such as venetoclax, may offer a new therapeutic avenue for BCL2-positive breast cancers." (PMID 37176102, 2023). "SGK1 was higher and Bcl-2 was lower in breast cancer tissue compared to normal breast tissue." (PMID 37370761, 2023). "Bcl-2 expression varied between histological or molecular subtypes of breast cancer." (PMID 37370761, 2023). "MIAT silencing could decrease Bcl-2 expression, viability, and proliferation of breast cancer cells and increase the expressions of cleaved caspase-3 and Bax." (PMID 37025425, 2023). "Therefore, miR-122-5p targets Bcl-2 and CDKs in breast cancer cells, which assists in cell-cycle arrest." (PMID 36803831, 2023). "Our group had previously reported that mir-195 was a circulating biomarker in breast cancer known to act as a tumor suppressor that targets Bcl-2 transcripts in HR+ breast cancers, actively regulating cell proliferation and the cell cycle and also aiding in the suppression of tumorigenicity." (PMID 36834918, 2023). "Bioinformatics analysis of in silico publicly available TNBC data identified BCL3 and BCL2 as well as the following anti-tumour immune response biomarkers as significantly altered in TNBC compared to other breast cancer subtypes: GZMA, PRF1, CXCL1, CCL2, CCL4, and CCL5." (PMID 38022682, 2023). "Another biomarker that is important to note in breast cancer is BCL2." (PMID 37176102, 2023). "Using a Bcl-2 antagonist (sabutoclax) could inhibit the IL-6/STAT3 signaling to resensitize Dox-resistant breast cancer in vitro and in vivo models." (PMID 37480115, 2023). "Here, we examined SGK1 and Bcl-2 protein expression in respective breast cancer tissue microarrays." (PMID 37370761, 2023). "Furthermore, RRS1 also induces apoptosis resistance in breast cancer cells through the ERK/Bcl-2/BAX signaling pathway." (PMID 37049702, 2023). "The main hypothesis is that the downregulation of GCR could alter SGK1 and Bcl-2 levels, which may contribute to the progression or aggression of breast cancer." (PMID 37370761, 2023).
breast carcinoma (continued). "Elucidating the function of the exposure of the Bcl-2-BH3 domain on tumor angiogenesis and exploring new Bcl-2-BH4 domain inhibitors to convert the function of Bcl-2 may provide a potential new strategy for anti-angiogenic therapy of breast cancer." (PMID 37237269, 2023). "Decreased Bax/Bcl-2 ratio and caspase activity are the main mechanisms that cause the malignant glioblastoma cell line U87MG to be resistant to temozolomide (TMZ) and the breast cancer cell line MCF-7 to be resistant to paclitaxel." (PMID 37742026, 2023). "Furthermore, TAMs induce doxorubicin resistance in breast cancer by upregulating IL-10 via the IL-10/IL10-receptor/STAT3/Bcl-2 signaling pathway." (PMID 37369757, 2023). "Combination of Pitavastatin or simvastatin with doxorubicin/ cyclophosphamide may induce apoptosis in breast cancer cells via upregulation of the Bax/Bcl2 pathway, potentially providing a promising new therapeutic strategy for breast cancer." (PMID 38051378, 2023). "Based on our findings, we propose that the Bcl-2 BH4 domain may be a target for the therapy of breast cancer." (PMID 37237269, 2023). "The research found that tanshinone IIA could promote MDA-MB-231 cell death in breast cancer via elevating the pro-apoptotic protein Bax and lowering the anti-apoptotic protein Bcl-2 levels." (PMID 37964867, 2023). "A few studies have considered the use of Bcl-2 as a prognostic marker for breast cancer." (PMID 37736508, 2023). "Amygdalin (5–20 mg mL−1) may trigger apoptosis in a concentration-dependent manner by increasing pro-apoptotic Bax protein and decreasing anti-apoptotic Bcl-2 protein in SK-BR-3 cells (HER2 overexpressing human breast cancer cell line)." (PMID 36291723, 2022). "BAX and BCL2 are known prognostic biomarkers for breast cancer." (PMID 35269511, 2022). "In addition, CPT inhibited STAT3, p-STAT3Ser727, p-STAT3Tyr705, c-Myc, and Bcl-2 expression in spontaneous Tientsin Albino two breast cancer mice." (PMID 35600860, 2022). "Furthermore, some selective HDAC inhibitors, such as PCI, vorinostat, and panobinostat are reported to enhance the expression of apoptosis factors (P21, cMYC, and BCL2) in breast cancers." (PMID 35453496, 2022). "It has been reported that Bcl-2 antagonized the autophagy pathway, subverted the internal protein quality and genome stability and promoted the growth of breast cancer cells, indicating that Beclin 1 and Bcl-2 can be served as attractive targets for cancer therapy." (PMID 36676047, 2022). "The induction of HDAC6 may be correlated with high BCL2 levels and paclitaxel resistance in luminal breast cancer." (PMID 35453496, 2022). "Notably, we observed prominent expressions of BCL-2 in lymphoma, myeloma, leukemia, lung, cervical, and breast cancer cell lines." (PMID 36358660, 2022). "Moreover, BCL2 phosphorylation at S70 directly regulates apoptosis by disrupting the binding to the proapoptotic protein in HER2-positive breast cancer cells." (PMID 35183115, 2022). "A prior study revealed that miR-195 is involved in promoting apoptosis in breast cancer and could attenuate the expression of Bcl2 via targeting its 3′UTR." (PMID 36192752, 2022). "A patented luteolin pharmaceutical composition from the USA has reported that the luteolin formulation prevents and treats the cancerous cells of liver, brain, pancreas, lung, breast cancer, and leukemia via targeting the BCL-2, bromodomains, sirtuins, kinases, and matrix metalloproteinases." (PMID 35458669, 2022). "Furthermore, some studies reported that Beclin 1 independent autophagy induction through Bcl-2 inhibitors, is observed in diseases like breast cancer and colorectal cancer by ABT-199 and obatoclax, respectively." (PMID 36309485, 2022). "Our present study clearly shows that DMF induces apoptosis through decreased Survivin, XIAP, Bcl-xL, and Bcl-2 expression via inhibition of NF-κB activation and potentiates the apoptosis-inducing effect of adriamycin and paclitaxel in human breast cancer cells." (PMID 35955813, 2022).
breast carcinoma (continued). "Tamoxifen upregulated Bcl-2 in PDX models of ER+ breast cancer, whereas ABT-737 and ABT-199 were found to elicit a response in PDX xenografts only in combination with tamoxifen, suggesting the requirement of Bcl-2 upregulation with tamoxifen for the activity of these BH3 mimetics." (PMID 35053443, 2022). "Moreover, IL-17RB and IL-17B amplification can promote tumorigenicity in breast cancer via the activation of NF-kB and Bcl-2." (PMID 35954312, 2022). "Interestingly, Bcl-2 is overexpressed in breast cancer and its pro-survival and pro-tumorigenic functions in breast cancer are correlated to its capacity to inhibit autophagy by binding to Beclin-1." (PMID 35884904, 2022). "Interestingly, we have previously reported that carnosol downregulated BcL-2 while upregulated Bax protein in MDA-MB-231 breast cancer cells." (PMID 35712465, 2022). "HOXA1 was found to upregulate the expression of BCL2 in breast cancer, which could also enhance cell proliferation and promote malignant transformation of cancer cells by activating STAT5a/b and MAPK signaling pathways." (PMID 35677036, 2022). "Overexpression of Bcl-2 has been observed in various breast cancer subtypes." (PMID 35053443, 2022). "Moreover, prognosis analysis revealed that breast cancer patients with high BCL2 levels had a better overall survival (p < 0.001)." (PMID 35251139, 2022). "Previous studies reported that overexpression of JAK2 in breast cancer promotes cancer cell survival and growth by modulating cell proliferation and apoptosis, partly through the upregulation of cyclin D1 and Bcl-2 family members, such as Bcl-xL and Bcl-2." (PMID 35269680, 2022). "The expression of BCL2 has been included in molecular panels determining the risk of recurrence and adjuvant treatment setting, such as Oncotype DX and PAM50-based–Prosigna Breast Cancer Prognostic Gene Signature Assay." (PMID 35053443, 2022). "The positive prognostic value of Bcl-2 has been mainly associated with early-stage breast cancer rather than advanced/metastatic cancer resistant to therapy." (PMID 35053443, 2022). "Bcl-2 is connected to the expression of estrogen and progesterone receptors, both favorable prognostic markers in breast cancer, and is expressed in about 75% of primary breast cancer malignancies." (PMID 35887080, 2022). "Moreover, Bcl-2 is related to the poor prognosis of primary central nervous system diffuse large B-cell lymphoma and breast cancer." (PMID 35473552, 2022). "Finally, the influence of HPex on increasing the expression of pro-apoptotic genes (Bad and Bax) and decreasing the expression of anti-apoptotic genes (Bcl-2) was highlighted in the breast cancer cell line—MCF-7." (PMID 35050083, 2022). "Breast cancer associated fibroblasts (bCAFs) are dependent upon MCL-1 for survival and through secretion of IL-6, bCAFs can induce upregulation of MCL1 mRNA and protein in luminal breast cancer cells to reduce sensitivity to BCL-2/XL inhibition." (PMID 35349392, 2022). "Interestingly, MDA-MB-231, an aggressive triple-negative subtype of breast cancer, showed competent levels of the BCL-2 protein." (PMID 36358660, 2022).
breast carcinoma (continued). "In addition to NF-κB signaling abrogation, blocking of Bcl-2 mRNA at the protein-mRNA level was discovered independently in human breast cancer cell lines." (PMID 36291832, 2022). "The high gene expression levels of BCL2 in this study could be a possible reason for the observed fast migration rates despite the cell-cycle arrest induced by AB1 in breast cancer cells." (PMID 36233156, 2022). "On the other hand, Bcl2 might provoke cellular metastasis in breast cancer through the epithelial to mesenchymal transition." (PMID 36299777, 2022). "Interestingly, for the anti-apoptosis proteins, a genetic alteration of Mcl-1, involving its amplification, is more common in breast cancer development than Bcl-2 and Bcl-xL amplification in clinical breast cancer datasets and is linked to a worse outcome." (PMID 35745769, 2022). "In various examples of human cancer lines such as prostate cancer, myeloid leukemia, breast cancer, glioblastoma etc., it has been demonstrated that they have heighten expression of multiple anti-apoptotic Bcl-2 proteins (Bcl-2, Bcl-XL and Mcl-1) and have displayed strong chemo resistance." (PMID 36267274, 2022). "In addition, AURKB inhibited the apoptosis of breast cancer cells by promoting Bcl-2 expression and inhibiting Bax expression." (PMID 36561847, 2022). "The frequent upregulation of pro-survival Bcl-2 proteins in luminal breast cancers suggests that these cancers could benefit from inhibitors targeting their activity." (PMID 35053443, 2022). "The natural compound, resveratrol seems to trigger caspase-independent cell death in MCF-7 breast cancer cells through changes in mitochondrial membrane potential, downregulating Bcl-2, increased ROS (reactive oxygen species) and nitric oxide production and prevention of NF-kB." (PMID 36234938, 2022). "Finally, transfection of tsRNA against BCL2, an anti-apoptotic factor into MCF7 breast cancer cells resulted in decreased levels of BCL2 protein." (PMID 35048990, 2022). "Furthermore, BITC has been shown to increase the expression of the pro-apoptotic proteins Bax and Bad while decreasing the expression of anti-apoptotic proteins Bcl-2 and Bcl-xL in breast cancer cells." (PMID 35684331, 2022). "Surprisingly, some of the compounds identified in the extract exhibited structural features that showed structural properties that predisposed them to possible interaction with the Bcl-2 receptor, which is overexpressed on cells of the breast cancer subtype called Bcl-2-enriched breast cancer." (PMID 36557944, 2022). "PCNA, Bax, and Bcl-2 have been confirmed by a large number of studies to be important proliferation and apoptosis proteins that can reflect the anti-tumor effect of drugs in breast cancer." (PMID 35911648, 2022). "Moreover, primaquine and chloroquine induce the apoptosis of breast cancer cells through c-Myc/Bcl-2 downregulation, induce early endosome damage and reduce nEGFR levels, and induce apoptosis in breast cancer through nEGFR/Stat3-dependent c-Myc downregulation." (PMID 34884765, 2021). "There are also studies conducted on promoter methylation states of 100 genes, including BRCA1, CCND2, BCL2, MDR1, IL10, and TWIST, recorded to understand how alteration between hypermethylation and hypomethylation over time contributes to select breast cancer susceptibility biomarkers." (PMID 34576196, 2021).
breast carcinoma (continued). "Besides, Bcl-2 is upregulated in approximately 50% of hormone-independent HER2+ breast cancers, which makes it a clinical prognostic marker in breast cancer." (PMID 34298639, 2021). "Our results are further supported by similar lapatinib-focused analyses of ER and BCL-2 co-expression, which demonstrated parallel upregulation of ER and BCL-2 within two pre-clinical models of treatment resistant HER2+ breast cancer as well as a subset of lapatinib-treated HER2+ clinical samples." (PMID 33951110, 2021). "For instance, the overexpression of the pro-survival Bcl-2 protein is common in TNBC breast cancer." (PMID 34298639, 2021). "Additionally, it was found that the Bcl-2 protein induces cell migration and invasion in a breast cancer cell line and also promotes metastasis to the lungs in a mouse model." (PMID 34142021, 2021). "Histone mRNAs HIST1H2AC, HIST1H2BF, and HIST1H2BO are shown to be overexpressed in breast cancer cells, contributing to the stability of the nucleosome structure for increased proliferation of cells and mediating the up-regulation of BCL2 expression to stimulated cell proliferation." (PMID 34502492, 2021). "Bcl-2 is overexpressed in half of the human malignancies and 50–70% of breast cancer patients." (PMID 33919902, 2021). "In this study, DBD-CAP resulted in the increase of the Bax/Bcl-2 ratio in both ER+ and ER- breast cancer cells suggesting that the observed cell apoptosis is dependent on alterations of these proteins expression and is associated with the mitochondrial apoptotic pathway." (PMID 35111687, 2021). "For example, METTL3 expression is elevated in breast cancer tissues and cells and can promote the multiplication of breast cancer cells and inhibit apoptosis by targeting Bcl-2; METTL3 upregulation promotes the metastasis of colorectal cancer cells through miR-1246/SPRED2/MAPK signaling pathway." (PMID 33818282, 2021). "In several publications, BCL-2 was determined to be an important promoter to regulate cancer stem cell-like behaviors in human breast cancer cells and consequently mediated multidrug (including trastuzumab) resistance of breast cancer cells." (PMID 33623790, 2021). "BCL2 was found in higher proportions in breast cancers of older women in study numbers #2 and #3." (PMID 34165702, 2021). "However, they also often overexpress pro-apoptotic proteins BAX or BAK: for example, BAX was reported to be overexpressed (alone or in combination with BCL-2) in about one third of breast cancers or in several pancreatic cancer cell lines." (PMID 33920941, 2021). "Since BCL2 is a putative oncogene in various malignant tumors, BCL2 expression has been hypothesized to have an adverse prognostic effect in breast cancers." (PMID 34099764, 2021). "Additionally, resveratrol has been shown to chemosensitize Adriamycin-resistant MCF-7 breast cancer cells to the drug, by targeting miR-122-5p, thus regulating apoptosis-inhibitory proteins Bcl-2 and CDKs." (PMID 33669559, 2021). "The knockdown of RPS15A by shRNA in breast cancer cell line ZR-75-30 and BT474 mediates apoptosis via the activation of caspase-3 and PARP cleavage, the up-regulation of Bad and BAX and the down-regulation of Bcl-2 confirming the importance of RPS15 in the modulation of breast cancer development." (PMID 34873618, 2021). "Utilizing these compounds as molecular tools to modulate BCL2 i-motif formation within B-cell lymphoma and breast cancer cell lines, BCL2 mRNA expression was substantially reduced, with less i-motif formation, while the presence of a stable i-motif increased mRNA levels." (PMID 33513764, 2021). "Since our results demonstrated similar BCL-2 enrichment within the context of HER2+/ER+ breast cancers, we would predict that HER2-targeted and ER-targeted treatments of these tumor types could be enhanced via venetoclax." (PMID 33951110, 2021).